SCYGR6 (small cysteine and glycine repeat containing 6)
Description:
In the hair cortex, hair keratin intermediate filaments are embedded in an interfilamentous matrix, consisting of hair keratin-associated proteins (KRTAP), which are essential for the formation of a rigid and resistant hair shaft through their extensive disulfide bond cross-linking with abundant cysteine residues of hair keratins. The matrix proteins include the high-sulfur and high-glycine-tyrosine keratins.
Synonyms: KRTAP28-6
Gene: Protein-coding gene on chromosome 2 (227,724,440 to 227,724,757, reverse strand). Ensembl gene ENSG00000284725.
Homologues: Orthologues: chimpanzee SCYGR6 (89% identical), pig SCYGR6 (84% identical), dog SCYGR6 (80% identical).